EYA2 (EYA transcriptional coactivator and phosphatase 2)
Diseases named in the same sentence as EYA2 in open-access papers (continued):
Sharing a sentence is not in itself a finding about the gene and the disease.
tumor (continued). "Consistent with the results of the tumor metastasis experiments, miR-338-3p inhibition or EYA2 knockdown markedly attenuated the ability of EGFR to regulate the EMT markers." (PMID 28703807, 2017). "After 11 weeks, we found that EYA2-overexpressing Panc2.5 cells showed a significant decrease in tumor weight (3-fold, P<0.0001) compared to control Panc2.5 cells." (PMID 24810906, 2014). "Recently, it has been found that EYA2 Tyr phosphatase inhibitors could reduce the mesenchymal phenotype, enhance the immunogenicity of tumor cells, weaken tumor growth, and increase the antitumor effects of anti-PD-1 in the mouse BC model by targeting FBOX7." (PMID 36750914, 2023). "SIX1 in cooperation with EYA2 promoted tumor cell metastasis by inducing TGF-β signaling and EMT." (PMID 36750914, 2023). "Moreover, we generated Eya2−/− mice and deletion of EYA2 aggravates tumor formation on HCC development in DEN-induced Eya2−/− mice, supporting our theory that EYA2 plays an essential role in the retard of initiation and progression of HCC." (PMID 34044846, 2021). "Notably, the growth rate and tumor weight of the subcutaneous transplanted human HCC-derived tumors with high EYA2 expression were significantly lower than those with low EYA2 expression in nude mice in vivo." (PMID 34044846, 2021). "Moreover, using hepatocyte-specific EYA2-knockout mice (Eya2−/−), we demonstrated that EYA2 acted as a tumor suppressor in the occurrence and progression of HCC through SOCS3-mediated blockade of JAK/STAT signaling." (PMID 34044846, 2021). "Specifically, the expression of EYA2 in adjacent tissues has a nuclear localization distribution, which may play a role in tumor-suppressive activities in the processes of intracellular signaling and transcription." (PMID 34044846, 2021). "In addition, immunohistochemistry and western blot analyses showed that the expression of EYA2 in the tumor tissues of the lentivirus-EYA2 group was significantly higher than that of control group." (PMID 34044846, 2021). "EYA2 knockdown significantly increased tumor growth and tumor weight." (PMID 34044846, 2021). "EYA2 is required for the ability of SIX1 in mediating tumor progression." (PMID 32258386, 2020). "On the contrary, tumor growth was suppressed when EYA2 was knocked down." (PMID 28703807, 2017). "EYA2 was reported to be up-regulated in epithelial ovarian cancer and promotes tumor growth." (PMID 29340020, 2017). "However, the effect of EGFR overexpression on tumor growth was dramatically attenuated when miR-338-3p was inhibited or EYA2 was knocked down." (PMID 28703807, 2017). "We further analyzed the role of EYA2 on tumor growth in vivo using an immunodeficient mouse model." (PMID 24810906, 2014). "Similarly, EYA2-overexpressing Panc3.014 cells totally lost their potential to form a tumor in vivo." (PMID 24810906, 2014). "Moreover, EYA2 promotes tumor progression in other tumors, including lung and osteosarcoma." (PMID 34044846, 2021). "Altogether, these results suggest that EYA2 acts as a tumor suppressor to prevent hepatocarcinogenesis and the malignant phenotype of HCC through the SOCS3-mediated blockade of JAK/STAT signaling, providing a molecular basis for the observed increased aggressiveness in EYA2 loss tumors." (PMID 34044846, 2021). "The imbalance of DACH1 and EYA2 may contribute to tumor initiation and development." (PMID 30761270, 2019). "Remarkably, through the miR-338-3p/EYA2 pathway, EGFR increased breast cancer cell growth, EMT, migration, invasion, and metastasis in an allograft tumor mouse model." (PMID 34206026, 2021). "MiR-30a has also been demonstrated to inhibit several critical oncogenes, such as Eya2, ITGB3, or UBE3C, and suppress tumor growth, cell migration and invasion." (PMID 29162923, 2017).
tumor (continued). "We performed qPCR on a subset of genes that were either among the most significant DEGs identified in our analysis of colon organoids of FAP versus healthy subjects and/or were significant in an analysis of either EOCRC tumor datasets: NKD1, EYA2, EGR2, EPDR1 and IGFL1." (PMID 36077675, 2022). "We sacrificed each cohort of induced mice at 7, 9, and 11 months, and liver tumors were found in 100% (3/3) of the Eya2−/− mice at 9 months after DEN treatment, whereas no obviously macroscopic tumor was found in the Eya2+/+ group." (PMID 34044846, 2021). "Furthermore, we analyzed EYA2 expression in HCC and adjacent non-tumor tissues using other three datasets downloaded from GSE22058, GSE14520 and ICGC_LIRI, which showed that the EYA2 mRNA expression was decreased in HCC compared with adjacent tissues." (PMID 34044846, 2021).
EYA2 also shares sentences with these, for which no sentence is quoted: colon carcinoma (3 papers); hepatocellular carcinoma (2); blood cancers (1); diabetes (1); diabetic nephropathy (1); diabetic retinopathy (1); gastrointestinal stromal tumor (1); invasive breast carcinoma (1); leukemia (1); lung fibrosis (1); lung squamous cell carcinoma (1); lymphoma (1); malignant peripheral nerve sheath tumor (1); metastatic cancer (1); multiple myeloma (1); myeloid leukemia (1); neuroblastoma (1); retinal degeneration (1); small cell lung carcinoma (1); thyroid cancer (1); Wilms tumor (1).